CRP (C-reactive protein)
Diseases named in the same sentence as CRP in open-access papers (continued):
Sharing a sentence is not in itself a finding about the gene and the disease.
Insulin resistance (continued). "However, we did observe that circulating CRP levels were positively related to body weight, visceral fat mass, and insulin resistance, while IL-6 and TNF-alpha were not related to any metabolic marker." (PMID 40218888, 2025). "Furthermore, individuals with insulin resistance, dyslipidemia, and MetS demonstrated higher plasma CRP concentrations compared to participants without these diagnoses." (PMID 39452916, 2024). "Breastfeeding duration was also related to lower CRP, and lower measures of insulin resistance (HOMA-IR) and insulin secretion (HOMA-B, AUCins/glu), as well as to increased overall insulin sensitivity (Matsuda) and insulin resistance-adjusted insulin secretion (ISSI-2)." (PMID 38772880, 2024). "Additionally, individuals with insulin resistance, dyslipidemia, and MetS showed higher plasma CRP concentrations than participants without these diagnoses." (PMID 39452916, 2024). "Moreover, FEV1 was significantly reduced at higher adiponectin levels, but this correlation was no longer significant after adjusting for insulin resistance and CRP." (PMID 38463522, 2024). "CRP, fibrinogen, and ESR were useful, but more specific investigations into aspects such as IL-6 and TNF-α may be necessary to better understand the role of insulin resistance in MetS." (PMID 38731059, 2024). "Furthermore, according to the SUCRA results, EHDS may be the best dosing strategy for vitamin D supplementation in terms of improving insulin resistance (HOMA-IR) and reducing inflammatory response (serum CRP)." (PMID 38160221, 2024). "Additionally, hesperidin demonstrated the ability to downregulate the expression of suppressor of cytokine signaling-3 (SOCS-3) and C-reactive protein (CRP) mRNA, both of which play pivotal roles in insulin resistance, and it also exhibited inhibitory effects on IL-6 production induced by LPS." (PMID 38234970, 2023). "Second, some risk markers were not included for performance assessment due to the lack of measurement, such as high-sensitivity C-reactive protein (hs-CRP) and homeostasis model assessment of insulin resistance (HOMA-IR), so this score should not be used without caution." (PMID 37914709, 2023). "Downregulation of CRP, TNF-α, and nitrites and upregulation of adiponectin could be responsible for LTBI mediated protection against insulin resistance (IR), while the high levels of IL-1β, IL-12, and leptin could be responsible for IR mediated anti-TB immunity." (PMID 35832818, 2022). "In contrast to prior studies, their results suggest that C-Reactive Protein levels may not have a meaningful effect on insulin resistance." (PMID 36265006, 2022). "However, the effect of CRP on other key nodes in the insulin signaling pathway such as the IR have not been researched to fully elucidate its role in insulin resistance." (PMID 35883605, 2022). "Insulin resistance and C-reactive protein (CRP) were not different between cohorts." (PMID 36079796, 2022). "Also, chronically elevated levels of inflammatory cytokines such as CRP, TNF-a, IL-6, and IL-1b could enhance insulin resistance (IR), disrupt insulin sensitivity, and consequently impair glucose homeostasis resulting in an increase in the risk of T2DM." (PMID 34917685, 2021). "We used CRP, an archetypal downstream inflammatory marker, as a means of gauging the effect of systemic inflammation in MVMR analysis, rather than hypothesising a specific role for CRP in the relationship between insulin resistance and schizophrenia." (PMID 33711016, 2021). "Adding omega-3 FAs to collagen was associated with clinical, but not statistical, improvement in insulin resistance and significant decrease of hs-CRP levels compared to the control group throughout the study, which suggests the synergistic effects of collagen and omega-3 FAs." (PMID 34405148, 2021).
Insulin resistance (continued). "In the study that analyzed the risk of CVD according to FM distribution in children and adolescents, FM in the trunk had a positive correlation with low HDL-C, high TG, insulin resistance, and high C-reactive protein, while FM in the leg showed a negative correlation." (PMID 34465815, 2021). "On the other hand, a Mendelian randomization study did not support a causal effect of the inflammatory marker C-reactive protein (CRP) in insulin resistance or T2D, although this does not exclude the possibility of a role of other upstream inflammatory effectors." (PMID 33261667, 2020). "hs-CRP level has been shown to predict changes in insulin sensitivity and future insulin resistance even in non-diabetic adults; thus, hs-CRP level may indicate the imminent development of type 2 diabetes." (PMID 33679598, 2020). "There are a large number of inflammatory mediators, such as C-reactive protein (CRP), interleukin-6 (IL-6), and plasminogen activator inhibitor-1 (PAI-1), that are elevated in the plasma of obese patients or animals and are closely related to insulin resistance." (PMID 31440472, 2019). "Our observations of higher LPS, CRP, TNF-α/IL-10 ratio, and HOMA-IR values in the omnivorous group reinforce previous hypothesis that a saturated fat-enriched diet could induce inflammation and insulin resistance." (PMID 28814977, 2017). "Elevated concentrations of various inflammatory markers in the circulation have been reported in humans with insulin resistance (IR), e.g., interleukin (IL)-1β, IL-6, tumour necrosis factor (TNF)-α, soluble TNF receptors (sTNFR1, sTNFR2), and C-reactive protein (CRP)." (PMID 26930607, 2016). "However, the present findings suggest that insulin resistance does not exert much influence on the relationship between adiposity, fitness and CRP as has been previously reported." (PMID 26075745, 2015). "Among participants without insulin resistance (n = 1141), adiponectin was also directly associated with PEA (β = 0.74 ± 0.23, p = 0.001), after adjustment for age, sex, BMI, waist circumference, HDL-cholesterol and CRP, as indicated by the stepwise procedure." (PMID 24575123, 2014). "Effect of fructose- induced insulin resistance (IR, 10% in drinking water, for 12 weeks) and daily oral administration of quercetin (50 mg.kg−1) on body weight, blood glucose, serum insulin, insulin resistance (IR) index, TNF-α, C-reactive protein (CRP), systolic BP." (PMID 23717483, 2013). "Insulin resistant morbid obese (IR-MO) subjects when compared to non insulin-resistant morbid obese (NIR-MO) group showed significantly larger waist circumference and higher levels of fasting insulin, HOMA-IR, HbA1C and CRP, while HDL cholesterol levels were lower." (PMID 24138787, 2013). "We evaluated insulin resistance, non-esterified fatty acid, high-sensitive CRP, estimated glomerular filtration rate, waist/hip ratio, abdominal visceral adipose tissue (VAT), subcutaneous adipose tissue (SAT) and other clinical characteristics in addition to glycemic control." (PMID 23446214, 2013). "MS: Metabolic syndrome; CRP: C-reactive protein; TG: Triglycerides; HDL-C: High-density lipoprotein cholesterol; TC: Total cholesterol; LDL-C: Low-density lipoprotein cholesterol; HOMA-IR: Homeostatic model assessment insulin resistance.; TNF-alpha: Tumor necrosis factor alpha; BMI: Body mass index." (PMID 22691465, 2012). "Finally, the pGDM women included in the present study did not perform blood tests comprehensive of C-reactive protein, N-terminal pro-B-type natriuretic peptide (NT-proBNP) and Homeostatic Model Assessment for Insulin Resistance (HOMA-IR), which were not foreseen in the research protocol." (PMID 40004801, 2025). "However, we could only evaluate the association of cMetS-S with insulin resistance (HOMA-IR) as the hallmark of Mets and data of other markers such as CRP, uric acid, and HbA1C was not available." (PMID 37160960, 2023).
Insulin resistance (continued). "Moreover, a systematic review discovered that VD intervention during pregnancy could change the blood levels of VD, fasting plasma glucose, homeostasis model of assessment for insulin resistance index (HOMA-IR), glutathione, C-reactive protein (CRP), and lipid." (PMID 36771240, 2023). "Indeed, OC treatment in AYAs with PCOS fails to normalise insulin resistance, the circulating levels of ultra-sensitive C-reactive protein (us-CRP, a marker of low-grade inflammation), the carotid intima-media thickness (cIMT, a marker of subclinical atherosclerosis) or the ectopic fat." (PMID 37715279, 2023). "Furthermore, it remains unclear whether the relationship between CRP and insulin resistance is independent of weight, body fat or fat-free mass in women with GDM." (PMID 37891561, 2023). "Notably, genera within Proteobacteria were negatively associated with multiple metabolic parameters (HOMA-IR, fasting serum insulin, low-density lipoprotein, triglycerides, and total cholesterol) and CRP and Akkermansia had negative correlations with weight, insulin resistance, and CRP." (PMID 35316158, 2022). "Increased inflammation, as most commonly adjudged by elevations in C-reactive protein (CRP), is associated with PCOS and has been reported even in normal weight women with PCOS (though at admittedly lower levels that their obese counterparts), although insulin resistance was not taken into account." (PMID 36079796, 2022). "Yangyinqingre formula decreased serum glucose, insulin resistance, serum creatinine, and proteinuria in DKD models, and this renoprotection function could be related to its action in anti-inflammation, which involves inhibition of expression of TNF-α, IL-17, VEGF and CRP." (PMID 31281401, 2019). "However, one study of 8-year-old children compared the effect of milk and meat consumption on insulin resistance, and found a positive association between milk (but not meat) consumption and insulin concentration (103 %), insulin resistance (75 %), and C-reactive protein (26 %)." (PMID 26574072, 2015). "Analogous analyses stratified by insulin resistance status within smoking and non-smoking PCOS subgroups revealed significant differences in Castelli indices I and II, the TyG index, and CRP concentrations in both subgroups." (PMID 41516208, 2025). "Total and percent truncal fat correlated positively (p < 0.05) with serum triglycerides, non-high-density lipid cholesterol, c-reactive protein (CRP), oral glucose tolerance test (OGTT), and measures of insulin resistance." (PMID 40781458, 2025). "Patients with long COVID exhibit elevated levels of HAMD, HAMA, and FF scores, as well as increased CRP, PGE2, GAL-GALR1 signaling, insulin resistance, PAI1, NSE, and S100B compared to individuals without long COVID." (PMID 40048451, 2025). "The two cohorts were weight and age-matched, and did not have insulin resistance, but subjects with PCOS did have hyperandrogenemia, with increased C-reactive protein (CRP, an inflammatory marker) and anti-Müllerian hormone (AMH)." (PMID 38397086, 2024). "(iv) There are no data about homeostasis model assessment‐insulin resistance index (HOMA‐IR), hs‐CRP, and details for excluding autoimmune diseases in our study." (PMID 39403113, 2024). "Because Homeostatic Model Assessment for Insulin Resistance (HOMA-IR) and high-sensitive C-reactive protein (hs-CRP) levels are not measured in all clinical settings, the MASLD criteria are more intuitive than the MAFLD criteria." (PMID 39409124, 2024). "These relationships particularly those concerning CRP during pregnancy, were independent of weight ( for VAT, insulin resistance and secretion indices, MetS; all p ≤ 0.032) and of body fat ( for VAT, MATSUDA, MetS; all p ≤ 0.038)." (PMID 37891561, 2023). "Those who were obese in the GDM group had significantly higher serum insulin, insulin resistance (HOMA-IR), LDL-C, and CRP, than those who were not obese." (PMID 35817936, 2022).
Insulin resistance (continued). "UK women without PCOS had higher systolic and diastolic blood pressures, and increased testosterone results (p < 0.01) compared to Middle Eastern women without PCOS who had higher inflammatory markers (WBC and CRP), HDL and insulin resistance (p < 0.001)." (PMID 33144665, 2020). "The WHR, blood pressure, total cholesterol, low density lipoprotein cholesterol, and C-reactive protein concentrations were lower in the non-obese NAFLD than obese NAFLD group, but homeostatic model assessment of insulin resistance (HOMA-IR) was similar." (PMID 32488147, 2020). "Similar to literature, in our study, we found that some inflammatory markers, such as WBC, neutrophil, CRP, NL ratio, and SII, were increased in breast cancer patients with insulin resistance compared to those without insulin resistance." (PMID 32907593, 2020). "Testosterone (p < 0.001), HDL (P < 0.002), CRP (p < 0.001) were higher in the Middle Eastern population, whilst glucose, WCC, insulin and insulin resistance no longer differed between the 2 cohort of PCOS women." (PMID 33144665, 2020). "In this study, CRP, IL-6, and TNF-α were significantly elevated in obese Egyptian type 2 diabetics and positively correlated with insulin resistance, non-HDL and triglycerides, key components of metabolic syndrome." (PMID 29099041, 2017). "In conclusion, in this study, CRP, IL-6, and TNF-α were significantly elevated in obese Egyptian type 2 diabetics and were positively correlated with insulin resistance, non-HDL and triglycerides." (PMID 29099041, 2017). "The differences in insulin resistance, HbA1c, glucose, and urate were still present, though smaller; differences in HDL cholesterol, triglycerides, C-reactive protein, and systolic blood pressure were greatly attenuated and no longer statistically significant." (PMID 25181492, 2014). "Non-fasting blood glucose level, serum insulin level, insulin resistance index, serum tumour necrosis factor-α (TNF-α) and serum C-reactive protein (CRP) were determined." (PMID 23717483, 2013). "Addition of pioglitazone to RA therapy improves insulin resistance and modestly reduces RA disease activity measured by DAS28-CRP and two of its components, patient-reported GH and CRP, but not DAS28-ESR or ESR." (PMID 24020899, 2013). "Addition of pioglitazone to RA therapy improves insulin resistance and modestly reduces RA disease activity measured by DAS28-CRP and two of its components, including patient-reported global health and CRP, but not DAS28-ESR or ESR." (PMID 24020899, 2013). "Several studies demonstrated that insulin resistance, as expressed by HOMA-IR, was significantly correlated with CRP concentrations in nondiabetic general populations." (PMID 21167068, 2010). "Positive correlations were also observed with highly sensitive C-reactive protein (hs-CRP), insulin, glucose, triglycerides, and Homeostasis Model Assessment of Insulin Resistance (HOMA-IR), and a negative correlation was found with high-density lipoprotein (HDL) cholesterol." (PMID 41598707, 2026). "Up to now, there are no reports on the pathophysiological mechanism of CRP in the progression of PCOS and whether CRP affects insulin resistance, glucose tolerance, and even hepatic glucose flux in PCOS." (PMID 37660067, 2023). "Besides, insulin levels, insulin resistance (HOMA-IR) and inflammatory markers (such as: CRP and IL-6) were not complete for all patients." (PMID 35193565, 2022). "Significant differences in anthropometric parameters, plasma adiponectin levels and insulin resistance were found in adult African Americans and Haitian Americans, with and without T2DM adjusted for age, sex, smoking, NSAIDs and Hs-CRP, living in and around Miami, FL." (PMID 31667161, 2014).
Insulin resistance (continued). "Furthermore, in the women with insulin resistance, intake of MOJ for 4 weeks reduced the plasma VCAM-1 levels (554.99 ± 15.63 to 545.31 ± 14.65 ng·mL−1, p = 0.039) but the plasma levels of ICAM-1, C-reactive protein, TNF-α, IL-6, and IL-10 were not significantly altered." (PMID 37469434, 2023). "Moreover, the significant increment of hs-CRP in non-obese Type 2 DM, and its positive correlation with HOMA-IR suggest that chronic inflammation may play a role in the development of insulin resistance and Type 2DM." (PMID 25276234, 2014). "The significant increment of serum hs-CRP levels in our non-obese Type 2 DM, and the positive correlation between hs-CRP and HOMA-IR suggest that chronic inflammation may play a role in the development of insulin resistance and Type 2DM." (PMID 25276234, 2014). "The aim of the study was to compare the circulating levels of oxLDL, CRP, and some adipokines in lean, overweight, and obese patients with T2DM, in order to analyze how these biomarkers vary with BMI and if any of them may track with insulin resistance, regardless of BMI." (PMID 24634792, 2013).